FABP4 (fatty acid binding protein 4)
Diseases named in the same sentence as FABP4 in open-access papers (continued):
Sharing a sentence is not in itself a finding about the gene and the disease.
Obesity (continued). "Collectively, these findings highlight FABP4 as a key driver of myometrial dysfunction in obesity and a potential therapeutic target for improving labor outcomes in obese pregnancies." (PMID 40192565, 2025). "Research indicates that inhibiting FABP4 activity can effectively reduce body weight and enhance insulin sensitivity in obesity models, thereby reinforcing the potential of FABP4 as a target for intervention in metabolic diseases." (PMID 40098612, 2025). "We investigated the impact of obesity on uterine contractions during late pregnancy and identified FABP4‐mediated cholesterol metabolism as a key pathway in vivo and in vitro levels." (PMID 40192565, 2025). "To further test the relationship between FABP4 and obesity‐induced IVDD, we established a FABP4‐overexpression mice model using lentivirus." (PMID 40090836, 2025). "FABP4, which is also found in adipocytes, regulates lipid transport and metabolism, which is considered to link obesity to various systemic diseases." (PMID 40002815, 2025). "Firstly, this present study showed that FABP4 was a critical factor to induce IVDD in an obesity state, and inhibiting FABP4 using BMS309403 showed promising therapeutic effects." (PMID 40090836, 2025). "For example, obesity induced by a high-fat diet increases the secretion of FABP4 from adipocytes and macrophages into the circulation where soluble FABP4 can directly target breast cancer, inducing ALDH1-mediated breast tumor stemness and invasiveness." (PMID 40106183, 2025). "The CON group exhibited significantly higher FABP4 expression compared to the NC group (p < 0.05), consistent with increased lipid accumulation in obesity." (PMID 40508039, 2025). "In summary, this study highlighted the pivotal role of the oncogenic FABP4/UCP2 axis and its association with unfavourable treatment outcomes, particularly in the context of obesity-related CRC." (PMID 39823981, 2025). "In the context of obesity, CRISPRi is employed to silence Fabp4, which regulates lipid binding and storage in adipocytes." (PMID 41150735, 2025). "Recent studies have shown that elevated levels of FABP4 are considered a prognostic marker in obesity and the development of breast cancer." (PMID 39859448, 2025). "Collectively, our results provide a potential therapeutic target, FABP4, for alleviating NPC dysfunction and ECM catabolism associated with obesity‐induced IVDD." (PMID 40090836, 2025). "In this study, an HFD-induced obesity animal model was used to evaluate the role of FABP4 in metabolic OA, as previous studies have demonstrated the effects of HFD in inducing OA." (PMID 41419794, 2025). "The results of IHC staining also showed that overexpression of FABP4 further exacerbated obesity‐mediated IVDD." (PMID 40090836, 2025). "By treating NPCs with PA, we were able to mimic the lipotoxic effects of obesity and investigate the role of FABP4 in mediating these effects." (PMID 40090836, 2025). "FABP4 can also facilitate obesity by enhancing fatty acid uptake and transport, regulating adipocyte differentiation, and being involved in inflammatory responses and insulin resistance, resulting in adipocyte hypertrophy." (PMID 41235334, 2025). "Taken together, FABP4 mediated obesity‐related IVDD via dysfunction mainly by activating AGEs/RAGE/NFκB signalling cascade." (PMID 40090836, 2025). "Substantial evidence indicates that serum FABP4 levels are significantly elevated in patients with metabolic disorders such as diabetes, insulin resistance, obesity, and atherosclerosis." (PMID 40407691, 2025). "To further explore the regulatory mechanism of FABP4 during obesity‐induced IVDD, we firstly evaluated the expression of FABP4 in mouse IVD tissue." (PMID 40090836, 2025). "In this study, RT‐qPCR and histological staining revealed that FABP4 was among the most upregulated FABPs in degenerated human NP tissue or human primary NPCs due to obesity." (PMID 40090836, 2025).
Obesity (continued). "Then, we evaluated the ingrowth of new blood vessels into IVD tissue in WT and FABP4‐KO mice of obesity‐induced IVDD." (PMID 40090836, 2025). "Our result is in line with previous reports showing increased levels of circulating FABP4 in individuals with obesity and in individuals with decompensated cirrhosis." (PMID 41392988, 2025). "Our findings align with previous research in the general population reporting higher FABP4 levels in women with obesity, and a reversal of this effect in patients who underwent a gastric bypass." (PMID 40759955, 2025). "The application of FABP4 neutralizing antibodies exhibited therapeutic potential in obesity‐related impairments in glucose metabolism and systemic inflammation." (PMID 40716098, 2025). "Mechanistically, obesity activated the mammalian target of rapamycin complex 1 (mTORC1), which upregulated FABP4 expression, leading to the accumulation of advanced glycation end‐products (AGEs) in intervertebral disc tissue." (PMID 40090836, 2025). "In the case of aP2/FABP4 KO male mice, the uncoupling of obesity from insulin resistance was attributed to a marked decrease in TNF-α expression in adipose tissue." (PMID 37961647, 2025). "Fatty acid-binding protein 4 (FABP4), a key immunometabolic regulator, has been implicated in promoting obesity- and age-related pathologies." (PMID 39843629, 2025). "Studies of FABP4 have focused on patient obesity, because of its aberrant expression in adipose tissue and differentiated adipocytes and macrophages." (PMID 40963862, 2025). "Recently, an inhibitor of fatty acid binding protein 4 (Fabp4) has been explored as a novel approach for treating obesity." (PMID 40904782, 2025). "Despite the critical role of FABP4 in obesity‐related IVDD, there are still several limitations that should be acknowledged." (PMID 40090836, 2025). "Fatty acid-binding protein-4 has a significant expression in adipocytes, and increased concentrations of FABP-4 are linked to diabetes, hypertension, obesity, and female gender." (PMID 39286683, 2024). "ADH1B also regulates FABP4 expression during subcutaneous adipocyte differentiation and is inversely correlated with obesity and insulin resistance." (PMID 39406990, 2024). "Interestingly, mice treated with BMS309403 exhibited reduced symptoms of diabetes, atherosclerosis and mammary tumor growth, suggesting that targeting FABP4 with small-molecular inhibitors might represent a promising approach for treating obesity-associated diseases." (PMID 39054536, 2024). "FABP4 is highly expressed in adipocytes and is involved in obesity-related metabolic diseases, including diabetes and atherosclerosis." (PMID 38784129, 2024). "In summary, our study provides a comprehensive examination of the correlation between circulating FABP4 levels and obesity, diabetes, and the influence of age, gender, and ethnicity." (PMID 38731797, 2024). "Dysregulated FABP4 expression in obesity can exacerbate cardiac dysfunction, impact vascular endothelial growth factor (VEGF) secretion, and lead to vascular disorders." (PMID 39291267, 2024). "Recognizing the pivotal role of FABP4 in metabolic disorders, it becomes crucial to investigate its relationship with variables such as age and ethnicity, particularly in regions where obesity and diabetes are prevalent." (PMID 38731797, 2024). "Also, it has been documented that the administration of FABP4 externally induces endoplasmic reticulum stress in HepG2 liver cells which can potentially establish a connection between hepatic insulin resistance and metabolic dysfunction associated with obesity." (PMID 39527497, 2024). "Our studies demonstrate that circulating adipose fatty acid binding protein (A-FABP, or FABP4) links obesity-induced dysregulated lipid metabolism and breast cancer risk, thus potentially offering a new target for breast cancer treatment." (PMID 39054536, 2024).
Obesity (continued). "In many recent studies, researchers have attempted to prevent obesity by altering the expression of the transcription factors that regulate adipogenic genes, such as those encoding FAS and FABP4." (PMID 39765714, 2024). "Also, one study found that fatty acid-binding protein 4 (that induces inflammation to promote cancer cell migration, invasion, and metastasis under obese conditions) was overexpressed in the serum of patients with obesity and was associated with poor overall survival in pancreatic cancer." (PMID 38398110, 2024). "FABP4 has been identified as a regulator of islet function in obesity, where higher levels of FABP4 are documented in individuals with obesity and FABP4 was shown to elevate insulin secretion." (PMID 38961153, 2024). "Increased levels of FABP4 in the bloodstream are correlated with some conditions such as obesity, dyslipidemia, atherosclerosis and renal dysfunction." (PMID 39527497, 2024). "Obesity is associated with a loss of UCP1 (brown-like phenotype marker) and/or elevation of FABP4 (white-like phenotype marker)." (PMID 38784129, 2024). "One can assume that for CRCPs with metabolic syndrome or metabolically healthy obesity, it is the FABP4+MMP9+MMP2-TIMP1- population of circulating sEVs that is the most optimal biomarker reflecting tumor angiogenesis." (PMID 37109070, 2023). "FABP4 regulates adipogenesis by downregulating PPARγ and attenuates the development of diet-induced obesity in mice." (PMID 37244925, 2023). "We can assume that for RPC patients with metabolic syndrome or metabolically healthy obesity, the FABP4+MMP9+MMP2-TIMP1- population of plasma sEVs is the most optimal biomarker reflecting tumor angiogenesis." (PMID 37109070, 2023). "Since the discovery that adipocytes secrete FABP4 and that circulating FABP4 is elevated in obesity, it has generally been presumed that adipocytes are the major source of plasma FABP4 and are responsible for its hormonal effects." (PMID 37279064, 2023). "DNA methylation can alter the expression of obesity-associated genes, such as neuropeptide Y (NPY), peroxisome proliferator-activated receptor gamma (PPARγ), fatty acid binding protein 4 (FABP4), and sterol regulatory element-binding protein-1 (SREBP-1)." (PMID 37627544, 2023). "Circulating FABP4 levels strongly correlate with obesity and metabolic pathologies in experimental models and humans." (PMID 37279064, 2023). "Functional studies will help unravel the regulation of TG levels by FABP4 in obesity and outline FABP4 as a target candidate for the control of HTG." (PMID 36769659, 2023). "FABP4 disruption in mouse models results in reduced basal and stimulated lipolysis and the administration of FABP4 inhibitors reduces plasma TGs in mice with diet-induced obesity." (PMID 36769659, 2023). "It has been repeatedly shown that circulating levels of FABP4 are related to important aspects of metabolic physiology and, in general, higher levels of plasma FABP4 are reported in obesity and inflammatory states." (PMID 37207357, 2023). "Sex-specific differences in FABP-4 in relation to CRC are plausible, as sex differences have also been observed in the association between general obesity and CRC risk, where stronger associations have usually been observed with BMI in men than in women." (PMID 37833736, 2023). "The results showed that BMSC‐Exos reduced body weight and iWAT accumulation and expression of obesity genes (Lpetin and FABP4) in obese mice." (PMID 37073893, 2023). "Circulating FABP4, which as noted is elevated in obesity, is considered an important factor promoting vascular inflammation and plaque deposition in the development of atherosclerosis." (PMID 37207357, 2023). "FABP4 was mainly expressed in adipocytes and macrophages and was involved in obesity-induced insulin resistance." (PMID 37260987, 2023).
Obesity (continued). "Fatty acid binding protein 4 (FABP4), a member of the cytoplasmic fatty acid binding protein multigene family is secreted by adipocytes and its expression increases in cases of obesity and the MetS." (PMID 35406450, 2022). "In line with this, increased plasma FABP4 levels have been proven to have direct correlations with IR, metabolic syndrome, obesity, dyslipidemia, hypertension, and diabetes mellitus." (PMID 35923855, 2022). "Since FABP4 plays a critical role in coordinating cellular metabolism and inflammatory responses, numerous efforts have been taken to develop FABP4 inhibitors to treat immunometabolic diseases such as obesity, diabetes, and atherosclerosis." (PMID 35909571, 2022). "In particular, FABP4 levels are elevated in metabolic disorders, including obesity and metabolic syndrome." (PMID 35899119, 2022). "The FABP4 knockout model has been shown to confer protection from insulin resistance (IR) despite dietary obesity." (PMID 35457171, 2022). "Fatty acid binding protein 4 (FABP4) is a new type of adipokine secreted by adipocytes that is related to lipolysis, and elevated serum FABP4 levels are related to obesity and IR." (PMID 36267567, 2022). "FABP4 expression levels are increased in obesity owing to the lipid-rich TME and hyperplastic state of adipocytes, thus promoting lipid trafficking from obese adipocytes to cancer cells." (PMID 36060264, 2022). "Results from both mouse models and clinical studies support that FABP4 plays a key role in promoting obesity-related breast cancer development." (PMID 36060264, 2022). "For example, FABP4 facilitates the stemness and aggressiveness of tumour cells via the IL-6/STAT3/ALDH1 axis in obesity-associated breast cancer." (PMID 35198079, 2022). "Consistent with increased circulating lipids and fatty acids in obesity, a 6-month WD induced increased expression of fatty acid and lipid transporters Cd36, Fabp4, Fabp5 and Abca1 in liver ECs, which was partially restored by the reversion diet." (PMID 36400935, 2022). "Altogether, fetuin-A and FABP4 have a synergistic action towards lipid deposition, and they have positive correlations with obesity, metabolic syndrome, and IR, but the relationship between them still needs further study." (PMID 35923855, 2022). "A role in coordinating the β-cell response to obesity has also been suggested for FABP4, whose levels are raised during obesity." (PMID 35628332, 2022). "Although initially thought to be only a cytoplasmic protein, FABP4 was discovered in the bloodstream, and its levels were found to be higher in pathological conditions such as obesity, diabetes, and metabolic syndrome." (PMID 35628332, 2022). "FABP4, as a key mediator for fatty acid trafficking, has been found to be crucial for obesity-induced acute myelocytic leukemia (AML) growth through deregulated DNA methylation." (PMID 35899119, 2022). "FABP4 knock-out mice were protected from the development of obesity, insulin resistance, and impaired glucose tolerance, and their adipocytes showed reduced lipolysis." (PMID 34839983, 2022). "Under obesity, the synthesis of FABP4 increases, and the FABP4 content is higher not only in tissues but also in the blood, which promotes the occurrence and development of various cancers." (PMID 36060264, 2022). "FABP4 is expressed mainly in adipocytes and has been widely studied in obesity metabolic syndrome and cardiovascular disease." (PMID 35189817, 2022). "Exalted circulating FABP4 content is strongly related to obesity, atherosclerosis, cardiovascular events, insulin resistance, hypertension and diabetes." (PMID 36060264, 2022). "In 1996, a study revealed that FFAs are relevant to the induction of insulin resistance and FABP4 plays a pivotal role in the connection between obesity and insulin resistance." (PMID 36060264, 2022). "The protective role of Omentin-1 against AT inflammation in obesity was investigated recently in FABP4-Cre-mediated Omentin-1 overexpression mice." (PMID 35909571, 2022).
Obesity (continued). "Circulating FABP4 functions as a tumor-promoting factor for obesity-related breast cancer through the IL-6/STAT3/ALDH1 pathway." (PMID 36060264, 2022). "In an HCC murine model with obesity, insulin resistance, and dyslipidemia, fatty acid binding protein 4 (FABP4) was enriched in intra-tumoral HSCs, contributing to hepatocarcinogenesis." (PMID 35158892, 2022). "Several signaling pathways regulated by FABP4 are involved in the obesity/cancer axis through complex cellular and molecular mechanisms." (PMID 36060264, 2022). "In animal models, combined deficiency of FABP4 and FABP5 ensures more excellent defence against insulin resistance, obesity, and atherosclerosis than mice deficient for either FABP4 or FABP5." (PMID 34529222, 2022). "FABP4fl/flpvillinCreT mice exhibited resistance to both DSS-mediated colitis and HFD-mediated obesity as compared to control FABP4fl/fl mice, implying that FABP4 also affects the composition of gut microbiota." (PMID 36519446, 2022). "Taken together, these data indicate that liver-derived FABP4 acts as a crucial factor in the development of obesity-induced metabolic stress (hepatosteatosis) to promote hepatocarcinogenesis." (PMID 36060264, 2022). "Under a pathological condition such as obesity-induced oxidative stress, fatty acid (palmitate) would have relatively high affinity for FABP4, which would facilitate glucagon secretion from α-cells." (PMID 34174950, 2021). "In several previous studies, serum FABP4 levels were shown to be obviously increased in obesity and patients with T2D." (PMID 34174950, 2021). "Previous studies have demonstrated that circulating FABP4 positively correlated with obesity, hypertension, dyslipidemia, insulin resistance, waist circumference, and atherosclerosis, all of which are traditional risk factors of cardiovascular disease (CVD)." (PMID 34789046, 2021). "The proinflammatory activity of FABP4 in macrophages has been reported previously in the context of obesity, atherosclerosis, and nonalcoholic fatty liver disease." (PMID 33690220, 2021). "Circulating FABP4 level is elevated in obese individuals and is an independent predictor for obesity-related cardiometabolic syndrome." (PMID 33690220, 2021). "Adverse effects of FABP4 in patients with obesity, metabolic syndrome or diabetes are supported by in vitro and in vivo observations." (PMID 34638803, 2021). "Mice deficient in FABP4 do not develop diet-induced insulin resistance or diabetes despite becoming obese, implying FABP4 plays a role in the molecular network that couples obesity with insulin resistance." (PMID 33479282, 2021). "Fabp4 is highly expressed in adipocytes and also exists in macrophages and dendritic cells, which is related to diseases such as obesity and insulin resistance." (PMID 33326461, 2020). "Adipose-selective Tet1 knockout mice generated by using Fabp4-Cre improves cold tolerance and increases energy expenditure and protects against diet-induced obesity and insulin resistance." (PMID 32855402, 2020). "The increased FABP4 level is correlated with a variety of pathophysiologies including type 2 diabetes, obesity, cardiac dysfunction, Cushing’s syndrome as well as ovarian and breast cancer." (PMID 33101287, 2020). "To confirm the anti-obesity effect of combined CO and RF in HFD-induced mice, we examined the mRNA of adipogenesis-associated genes Cebpa, Fabp4, Pparg and Srebp1 in white fat tissue." (PMID 32443487, 2020). "With respect to lipid metabolism we expected a down-regulation in LPL and FABP4 expression in AT with increasing obesity." (PMID 32321549, 2020). "Lipid transport protein expressions, e.g. lipoprotein lipase (LPL) and fatty acid binding protein 4 (FABP4), are altered in human obesity." (PMID 32321549, 2020). "FABP4 is produced and released into the blood by adipocytes, a phenomenon correlated with obesity, which indicates that this chaperone can be pathogenic in the metabolic syndromes." (PMID 32856199, 2020).